KPNA2 (karyopherin subunit alpha 2)
Diseases named in the same sentence as KPNA2 in open-access papers (continued):
Sharing a sentence is not in itself a finding about the gene and the disease.
cancer (continued). "For example, KPNA2 was shown to be upregulated across a broad-spectrum of cancer types." (PMID 23536776, 2013). "To explore whether Oct4 and KPNA2 play a role in cancer cell growth, we employed an RNA interference approach to knockdown Oct4 and KPNA2 expression in both A549 and SPC cell lines." (PMID 24070213, 2013). "In addition, KPNA2 was identified as a potential biomarker for non-small-cell lung cancer (NSCLC) by integration of the cancer cell secretome and tissue transcriptome." (PMID 24070213, 2013). "Could KPNA2 expression lead to a significant activity in cancer cells to produce oncogenic inflammatory mediators?" (PMID 23536776, 2013). "When treated with cisplatin and 5-fluorouracil (5-FU), 344SQ cells cocultured with Kpna2-overexpressing LFs were more resistant to these anticancer drugs than those cocultured with control LFs, suggesting that KPNA2-high CAFs endow cancer cells with drug resistance." (PMID 35884546, 2022). "In line with the molecular functions of the selected genes modulating transcription (BPTF, DDX21), protein translation (NOLC1, TCOF1), or nuclear import (KPNA2) it is feasible to speculate that restoring their cellular content in cancer cells could facilitate viral production." (PMID 34203557, 2021). "Even though down‐regulation of KPNA2 could significantly repress cancer cell proliferation and further invasion ability, we found that overexpression of NPM1 could promote cell proliferation, as well as the migration ability and invasion of cancer cells in some degree." (PMID 34469024, 2021). "Therefore, it has been hypothesized that KPNA2 is a novel target related to resistance against cancer therapy." (PMID 31212646, 2019). "Moreover, KPNA2 is a molecule which could be antagonized permitting therapeutic intervention in cancer models." (PMID 30323892, 2018). "KPNA2 expression may be a useful prognostic biomarker to monitor cancer prognosis." (PMID 27974678, 2017). "However, this speculation needs experimental verification in the future to expand our understanding of the functions of KPNA2 in different cancers." (PMID 28422734, 2017). "Nevertheless, the regulation of KPNA2 expression in cancers remains unclear." (PMID 27009856, 2016). "However, the precise roles of KPNA2 in cancer cells require further investigation." (PMID 27078844, 2016). "The biological functions of KPNA2 have been examined in some cancer cell lines; for example, overexpression of KPNA2 in a benign breast cell line could increase cell colony formation ability and migration activity in a manner similar to that in malignant cells." (PMID 26204489, 2015). "It has been reported that KPNA2, which is an important RBP, is involved in mRNA metabolic processes that promote cancer cell proliferation and invasion." (PMID 39060340, 2024). "For example, the N-terminus is sufficient to interact with KPNA2 for TXNIP’s localization to the nucleus, while the C-terminus of TXNIP is critical for interactions with COPS5, to inhibit cancer cell proliferation." (PMID 38727583, 2024). "In this study, we demonstrate that KPNA2 silencing effectively blocked CSCs and that its presence was also required for increased ISGyaltion to promote ATC cancer stem cell-like characteristics." (PMID 37501099, 2023). "We performed immunohistochemical analysis of ACAT2, SPHK1, SNED1, KPNA2, BZW2 and KIF15 in cancer and normal tissues and statistically analyzed the staining intensity." (PMID 37202800, 2023). "In this study, we found that ISG15-mediated ISGylation of KPNA2 inhibited its ubiquitination degradation, thereby promoting nuclear translocation of c-MYC and maintaining cancer stem-like characteristics in ATC." (PMID 37501099, 2023). "We analyzed and confirmed the binding of KPNA2 to ISG15 and its ISGylation by mass spectrometry and experiments, and further identified KPNA2 as the mediator of ISG15 in modulating the cancer stem-like characteristics of ATC." (PMID 37501099, 2023).
cancer (continued). "Among these, Kpna2 expression was higher in murine CAFs than in normal lung fibroblasts and was indispensable for CAF-promoted cancer cell invasion." (PMID 35884546, 2022). "KPNA2 levels correct with HPV 16 markedly regulated cell differentiation, several oncogenes, and cancer‐related pathways." (PMID 35860570, 2022). "Several publications have reported the relationships between these five ER-related genes (SPP1, KIF2C, LPCAT1, KPNA2, and FMO3) and cancers." (PMID 35915607, 2022). "This study reveals that a specific subpopulation of CAFs confers anticancer drug resistance to cancer cells, suggesting the possibility of developing new anticancer drugs targeting specific markers of the CAF subpopulation, such as KPNA2." (PMID 35884546, 2022). "KPNA2 is a direct target of miR-139 and it can promote HCC growth likely via regulating nucleus transport of cancer-related proteins." (PMID 31046781, 2019). "Thus, it is not unexpected that KPNA2 has been linked to cancer." (PMID 28422734, 2017). "The core iCAMP gene set reproduces many well-established genes that are aberrantly expressed in cancer tissue, such as VCAN and KPNA2." (PMID 23536776, 2013). "Previous reports have demonstrated KPNA2 overexpression in various tumors cells in vitro and in vivo; elevated KPNA2 and KPNB1 expression in cancer cells correlates with altered transcriptional regulation associated with deregulated E2F/Rb activities." (PMID 24098495, 2013). "In addition, the detailed mechanism of KPNA2 and NPM1 as an oncogenic factor in cancer cells should be evaluated in future studies." (PMID 34469024, 2021). "According to a previously published report 45, KPNA2 is essential for some cancer, whereas it is not essential for some cancer." (PMID 34469024, 2021). "The MRN complex, which contains representative KPNA2 cargo proteins, was expressed in both noncancerous and cancer tissues." (PMID 28178675, 2017). "Overall, for both Oct4 and KPNA2, positive immunostaining was only observed in the nuclei of the cancer cells, whereas all the precancerous tissues showed negative staining." (PMID 24070213, 2013). "This indicates that Oct4 and KPNA2 could represent novel biomarkers for distinguishing cancer from noncancerous lesions." (PMID 24070213, 2013). "KPNA2 is an embryonic antigen, shown to be expressed in mouse embryonic stem cells and normal human testis, and emerges again in a variety of epithelial and non-epithelial cancers." (PMID 23536776, 2013). "Thus, we focused on karyopherin-α2 (KPNA2), which participates in the nuclear transport of the MRN complex and which is specifically expressed in cancer cells and embryonic stem cells, but not in most normal cells." (PMID 28178675, 2017).
infection (10 papers, 2013 to 2025). The state of being infected such as from the introduction of a foreign agent such as serum, vaccine, antigenic substance or organism. "Using siRNA, the expression level of KPNA2 was suppressed in both of the two cell lines, resulting in the reduced protein after 5 days infection." (PMID 34469024, 2021). "At early infection stage (at 24 h post infection), genes contributing to the nuclear transport like KPNA2 and KPNB1, RNA splicing gene SF3B4 were down-regulated compared with the normal control." (PMID 23451031, 2013). "As A55 is a predicted BBK E3 ligase adaptor, the levels of KPNA2 following infection with the WT VACV WR strain expressing A55 (vA55), a mutant lacking the A55R gene (vΔA55), or a revertant virus with A55R inserted back into vΔA55 and under its endogenous promoter (vΔA55Rev) were investigated." (PMID 30814284, 2019). "Interestingly we detected another family of nuclear transporter KPNA1, KPNA2, and KPNA4 to be significantly decreased at the later time point of infection." (PMID 34006825, 2021). "Notably, the levels of KPNA2 did not alter during infection or transfection." (PMID 30814284, 2019). "In addition, the expression levels of KPNB1, KPNA1, KPNA2, KPNA4, KPNA6, and KPNA7 changed with the infection time of the three strains while KPNA3 and KPNA5 did not change with the incubation time." (PMID 40687856, 2025).
adenocarcinoma (4 papers, 2016 to 2022). A common cancer characterized by the presence of malignant glandular cells. "However, quantitative differences in the expression of Tk1, Top2a, Hmgb2, Rrm2, Kpna2, and H1fx were observed and were found to be strongly up-regulated in small-sized adenocarcinomas." (PMID 27602772, 2016). "Notably, 4 of the glucose metabolism-related genes, GPI, G6PD, PKM2, and GAPDH and 5 of the cell cycle-related genes, ANLN, PTTG1, CIT, KPNA2, and CDC25A, were significantly down-regulated in EGFR m+ adenocarcinomas, and showed a substantial correlation with SUVmax." (PMID 28422979, 2017).
KPNA2 also shares sentences with these, for which no sentence is quoted: adenoma (2 papers); chondrosarcoma (2); Ewing sarcoma (2); gastric adenocarcinoma (2); upper tract urothelial carcinoma (2); anaplastic astrocytoma (1); bacterial infection (1); bladder (1); bone sarcoma (1); Bowen’s disease (1); brain tumor (1); breast (1); Burkitt lymphoma (1); cerebral astrocytoma (1); cervical tumor (1); chondroblastoma (1); clear cell renal cell carcinoma (1); coronary artery disease (1); embryonal carcinoma (1); endothelial dysfunction (1); Epstein-Barr virus infection (1); head/neck squamous cell carcinoma (1); HIV-1 infection (1); inflammatory skin disease (1); intraductal papillary mucinous neoplasms (1); invasive lobular breast carcinoma (1); laryngeal squamous cell carcinoma (1); lung squamous cell carcinoma (1); metastatic tumors (1); mixed germ cell tumor (1).
A further 15 diseases each share a sentence with KPNA2 in 1 paper.